SLC13A4 (solute carrier family 13 member 4)
Description:
Sodium:sulfate symporter that mediates sulfate reabsorption in the high endothelial venules (HEV).
Synonyms: SUT1; SUT-1; NAS2
Tractability: Antibody: its Gene Ontology location is reachable by antibodies, with high confidence; UniProt predicts a signal peptide or a membrane-spanning region.
Gene: Protein-coding gene on chromosome 7 (135,681,231 to 135,729,258, reverse strand). Ensembl gene ENSG00000164707.
Subcellular location: Membrane
Pathways (Reactome):
Transport of small molecules: Sodium-coupled sulphate, di- and tri-carboxylate transporters
Gene Ontology:
Molecular function: protein binding; sodium:sulfate symporter activity; solute:sodium symporter activity; transmembrane transporter activity
Biological process: sulfate transmembrane transport; transmembrane transport; sodium ion transmembrane transport
Cellular component: plasma membrane; membrane
Genetic constraint (gnomAD): Loss-of-function variants: 20 observed, 62.09 expected, observed/expected ratio (o/e) 0.32, 90% interval 0.23 to 0.47. The upper end of that interval is the gene's LOEUF score, 0.47, which puts it in group 2 of 6, group 1 being the genes least tolerant of losing a copy. Missense variants: 600 observed, 747.55 expected, observed/expected ratio (o/e) 0.8, 90% interval 0.75 to 0.86. Synonymous variants: 286 observed, 309.94 expected, observed/expected ratio (o/e) 0.92, 90% interval 0.84 to 1.02.
Homologues: Orthologues: chimpanzee SLC13A4 (99% identical), macaque SLC13A4 (98% identical), dog SLC13A4 (93% identical), pig SLC13A4 (90% identical), rat Slc13a4 (89% identical), mouse Slc13a4 (89% identical), guinea pig SLC13A4 (89% identical), rabbit SLC13A4 (80% identical), tropical clawed frog slc13a4l (72% identical), zebrafish slc13a4 (65% identical), Caenorhabditis elegans nac-1 (32% identical), Caenorhabditis elegans nac-3 (30% identical), and 6 more. Paralogues in human: SLC13A1 (47% identical), SLC13A2 (39% identical), SLC13A5 (39% identical), SLC13A3 (36% identical), OCA2 (15% identical).
Diseases named in the same sentence as SLC13A4 in open-access papers:
SLC13A4 is named in the same sentence as 27 diseases in open-access papers, as found by Europe PMC text mining. Sharing a sentence is not in itself a finding about the gene and the disease. The quoted sentences say what the papers report.
breast carcinoma (1 paper, 2021). "SLC13A4 expression was lower in breast cancer, head and neck squamous cell carcinoma, kidney chromophobe, thyroid cancer, and higher in renal clear cell carcinoma, hepatocellular carcinoma, cholangiocarcinoma, and rectal adenocarcinoma." (PMID 34840533, 2021).
esophageal cancer (1 paper, 2021). A primary or metastatic malignant neoplasm involving the esophagus. "SLC13A4 expression was higher in lymphoma tissues than in adjacent tissues, and was lower in esophageal cancer, HNSCC and sarcoma." (PMID 34840533, 2021).
head and neck squamous cell carcinoma (1 paper, 2021). A squamous cell carcinoma that arises from any of the following anatomic sites: lip and oral cavity, nasal cavity, paranasal sinuses, pharynx, larynx, and salivary glands. "SLC13A4 expression in Head and neck squamous cell carcinoma (HNSCC) was closely related to tumor pathological grade and clinical stage." (PMID 34840533, 2021).
schizophrenia (1 paper, 2022). A major psychotic disorder characterized by abnormalities in the perception or expression of reality.
viral diseases (1 paper, 2021). "In addition, the genes in SLC13A4 low-expression group were mainly concentrated in immunity-related activities, viral diseases, typical tumor pathways and metabolism." (PMID 34840533, 2021).
cancer (3 papers, 2021 to 2024). A tumor composed of atypical neoplastic, often pleomorphic cells that invade other tissues. "TCGA, Oncomine and Timer databases were used to analyze SLC13A4 mRNA expression in cancer tissues and normal tissues, and its correlation with clinical prognosis in head and neck tumor." (PMID 34840533, 2021). "However, there were no enrichment of genome sets involving immune-related activities and typical tumor pathways in the high SLC13A4 expression group, which further suggested that low SLC13A4 expression might be implicated in the process of cancer development and immune activities." (PMID 34840533, 2021). "We theorize that SLC13A4 expression is related to the prognosis of cancer patients." (PMID 34840533, 2021).
head and neck tumors (1 paper, 2021). "SLC13A4 mRNA levels were significantly lower in head and neck tumors than in paracancer tissues." (PMID 34840533, 2021).
neurodevelopmental disorder (1 paper, 2022). A behavioral and cognitive disorder with onset during the developmental period that involves impaired or aberrant development of intellectual, motor, or social functions. "Dysregulated SLC13A4 expression has been observed in several neurological and neurodevelopmental disorders and during seizures, which display shared phenotypes with AS patients." (PMID 36012404, 2022).
tumor (1 paper, 2021). "In HNSCC patients, the expression of SLC13A4 decreased with the increase of tumor pathological grade and clinical stage." (PMID 34840533, 2021). "On the basis of its expression in thymus, we further analyzed the potential pathways and possible molecular mechanisms by which SLC13A4 is involved in HNSCC tumor immune infiltration by searching cibersort and GSEA database." (PMID 34840533, 2021). "Tumor samples were divided into a high and a low expression group according to the median expression of SLC13A4." (PMID 34840533, 2021). "According to the median mRNA value of SLC13A4 expression, tumor samples were divided into a high expression group and a low expression group." (PMID 34840533, 2021). "SLC13A4 expression showed statistically significant differences among T stage, N stage and pathological grades, exhibiting an overall tendency that the more malignant the tumor, the lower the mRNA expression of SLC13A4." (PMID 34840533, 2021). "These suggest that SLC13A4 might reverse T cell immunosuppression and inhibit tumor immune escape." (PMID 34840533, 2021). "Furthermore, the expression of SLC13A4 in HNSCC is negatively correlated with a variety of T cell exhaustion markers, including LAG3 ( p < 0.001), TIM-3( p < 0.001) and CTLA-4 ( p < 0.001), indicating its potential mechanism in regulating tumor immunity." (PMID 34840533, 2021). "However, there was no genomic enrichment involving immunity and typical tumor pathways, suggesting that SLC13A4 might act as an indicator of TME transformation from metabolic dominance to immune dominance." (PMID 34840533, 2021).
SLC13A4 also shares sentences with these, for which no sentence is quoted: infection (4 papers); iron deficiency (2); Autoimmunity (1); cholangiocarcinoma (1); hepatocellular carcinoma (1); Hypertension (1); intraventricular haemorrhage (1); iron (1); kidney chromophobe (1); lymphoma (1); metabolic syndrome (1); rectal adenocarcinoma (1); renal clear cell carcinoma (1); retinopathy of prematurity (1); sarcoma (1); tauopathy (1); thyroid cancer (1); viral myocarditis (1).